KBTBD11 (kelch repeat and BTB domain containing 11)
Synonyms: KIAA0711; KLHDC7C
Tractability: Small molecule: it belongs to a druggable protein family. PROTAC: ubiquitination databases record sites on it; its protein half-life has been measured.
Gene: Protein-coding gene on chromosome 8 (1,973,677 to 2,006,937, forward strand). Ensembl gene ENSG00000176595.
Subcellular location (Human Protein Atlas): Intermediate filaments
Genetic constraint (gnomAD): Loss-of-function variants: 3 observed, 1.44 expected, observed/expected ratio (o/e) 2.09. That is too few expected variants to judge how well the gene tolerates losing a copy. Missense variants: 1,390 observed, 658.56 expected, observed/expected ratio (o/e) 2.11. Synonymous variants: 747 observed, 360.46 expected, observed/expected ratio (o/e) 2.07.
Homologues: Orthologues: chimpanzee KBTBD11 (99% identical), mouse Kbtbd11 (82% identical), rat Kbtbd11 (81% identical), pig KBTBD11 (78% identical), guinea pig KBTBD11 (74% identical), tropical clawed frog kbtbd11 (47% identical), zebrafish kbtbd11 (42% identical). Paralogues in human: KLHDC7B (34% identical), KLHDC7A (31% identical), KLHL42 (20% identical), KLHL26 (19% identical), KLHL21 (19% identical), KLHL1 (19% identical), KLHL4 (19% identical), KLHL9 (19% identical), KLHL33 (19% identical), KLHL22 (19% identical), KLHL34 (19% identical), KLHL13 (18% identical), and 42 more.
Diseases named in the same sentence as KBTBD11 in open-access papers:
KBTBD11 is named in the same sentence as 10 diseases in open-access papers, as found by Europe PMC text mining. Sharing a sentence is not in itself a finding about the gene and the disease. The quoted sentences say what the papers report.
colorectal cancer (2 papers, 2019 to 2022). A primary or metastatic malignant neoplasm that affects the colon or rectum. "A variant allele of KBTBD11—rs11777210—is significantly associated with cell susceptibility to colorectal cancer." (PMID 31844712, 2019).
colon cancer (1 paper, 2022). "KBTBD11 is a tumor suppressor gene that has been identified as differentially expressed in MTX-resistant colon cancer cell lines." (PMID 35639775, 2022).
microcephaly (1 paper, 2021). A congenital or acquired developmental disorder in which the circumference of the head is smaller than normal for the person's age and sex. "In particular, ARHGEF10 is involved in neuronal morphogenesis and DECIPHER Patient 368323, which carries an ARHGEF10 SNV, presents microcephaly; CSMD1 and KBTBD11 are brain-specific expressed genes, and CSMD1 is also dosage-sensitive." (PMID 33925474, 2021).
Obesity (1 paper, 2019). Accumulation of substantial excess body fat. "Considering that Kbtbd11 is a target USF1 gene that regulates proliferation and differentiation in adipocytes, genetic variation in USF1 and varying Kbtbd11 expression levels could be associated with obesity." (PMID 31844712, 2019). "We have previously reported that Kbtbd11 is involved in nutritional regulation and is highly expressed in the epididymal white adipose tissue (eWAT) in diet-induced obesity (DIO) mice compared with that in mice fed on chow diet." (PMID 31844712, 2019). "Cell biology; Cell Differentiation; Gene Expression; Gene Regulation; Transcription Factor; Biochemistry; Molecular Biology; Obesity; Kbtbd11; 3T3-L1 differentiation; USF1; transcriptional regulation." (PMID 31844712, 2019). "We have previously reported that Kbtbd11 mRNA expression increases in a time-dependent manner during 3T3-L1 differentiation and increases significantly in eWAT under feeding status and obesity." (PMID 31844712, 2019).
tumor (3 papers, 2019 to 2022). "KBTBD11 expression is significantly decreased in tumor tissues compared with adjacent paired normal tissues." (PMID 31844712, 2019). "KBTBD11 is reported to be downregulated in tumor tissues, and KBTBD11 knockdown promoted cell proliferation and inhibited cell apoptosis, suggesting that regulation of KBTBD11 expression and transcript levels of KBTBD11 play important roles in tumorigenesis and function." (PMID 31844712, 2019).
KBTBD11 also shares sentences with these, for which no sentence is quoted: cancer (3 papers); acute lymphoblastic leukemia (1); B-cell acute lymphoblastic leukemia (1); coronary artery disease (1); leukemia (1).